GLIPR2 (GLI pathogenesis related 2)
Synonyms: GAPR-1; GliPR 2; C9orf19; GAPR1
Tractability: Antibody: its Gene Ontology location is reachable by antibodies, with medium confidence. PROTAC: ubiquitination databases record sites on it; its protein half-life has been measured.
Gene: Protein-coding gene on chromosome 9 (36,136,536 to 36,163,913, forward strand). Ensembl gene ENSG00000122694.
Subcellular location: Golgi apparatus membrane
Subcellular location (Human Protein Atlas): Vesicles; Microtubules
Gene Ontology:
Molecular function: protein homodimerization activity
Biological process: positive regulation of epithelial cell migration; positive regulation of epithelial to mesenchymal transition; positive regulation of ERK1 and ERK2 cascade
Cellular component: extracellular exosome; Golgi membrane; extracellular region
Genetic constraint (gnomAD): Loss-of-function variants: 8 observed, 6.69 expected, observed/expected ratio (o/e) 1.2, 90% interval 0.69 to 1.86. That is too few expected variants to judge how well the gene tolerates losing a copy. Missense variants: 118 observed, 118.13 expected, observed/expected ratio (o/e) 1, 90% interval 0.86 to 1.16. Synonymous variants: 50 observed, 49.72 expected, observed/expected ratio (o/e) 1.01, 90% interval 0.8 to 1.27.
Homologues: Orthologues: macaque GLIPR2 (99% identical), rabbit GLIPR2 (97% identical), chimpanzee GLIPR2 (96% identical), pig GLIPR2 (95% identical), mouse Glipr2 (94% identical), rat Glipr2 (93% identical), guinea pig GLIPR2 (92% identical), zebrafish glipr2l (73% identical), tropical clawed frog glipr2 (47% identical), Drosophila melanogaster CG31482 (44% identical), Caenorhabditis elegans F09B9.5 (35% identical). Paralogues in human: CRISP2 (26% identical), CRISPLD2 (26% identical), GLIPR1L1 (26% identical), CRISP3 (25% identical), PI15 (25% identical), CRISP1 (24% identical), CLEC18A (23% identical), CLEC18B (23% identical), CLEC18C (23% identical), R3HDML (23% identical), CRISPLD1 (23% identical), GLIPR1L2 (22% identical), and 1 more.
Diseases named in the same sentence as GLIPR2 in open-access papers:
GLIPR2 is named in the same sentence as 29 diseases in open-access papers, as found by Europe PMC text mining. Sharing a sentence is not in itself a finding about the gene and the disease. The quoted sentences say what the papers report.
glioma (3 papers, 2013 to 2025). A benign or malignant brain and spinal cord tumor that arises from glial cells (astrocytes, oligodendrocytes, ependymal cells). "Our investigation into the expression of GLIPR2 has uncovered a positive correlation with immune scores in several cancer types, including low-grade glioma (LGG), CESC, LUAD, as well as other neoplastic tissues." (PMID 38476239, 2024). "Glioma pathogenesis related-2 (GLIPR-2) belongs to pathogenesis related-1 (PR-1) family whose function remains unknown." (PMID 24204846, 2013).
renal fibrosis (3 papers, 2013 to 2023). A final common manifestation of a wide variety of chronic kidney diseases characterized by glomerulosclerosis and tubulointerstitial fibrosis. "In our previous studies, GLIPR-2 was found to be a novel potent stimulator of epithelial-to-mesenchymal transition (EMT) in renal fibrosis which has been classified as type 2 EMT." (PMID 24204846, 2013). "GLIPR-2 may be responsible for the development of renal fibrosis by increasing the accumulation of interstitial fibroblasts." (PMID 23516513, 2013). "Our previous studies have shown that GLIPR-2 was highly expressed in proximal renal tubular epithelial cells in diabetic nephropathy and overexpression of GLIPR-2 in HK-2 cells promotes EMT in vitro via ERK1/2 signaling pathway, which was classified as type 2 EMT involved in renal fibrosis." (PMID 24204846, 2013).
viral infections (3 papers, 2013 to 2021). "GLIPR-2 belongs to the PR-1 protein family, which was first identified in plants during the acquisition of resistance to viral infections." (PMID 23516513, 2013). "GLIPR-2 was first found in acquisition of resistance by plants against viral infections and has been reported widely expressed in the mammalian and plant." (PMID 24204846, 2013).
cholangiocarcinoma (2 papers, 2023 to 2024). A carcinoma that arises from the intrahepatic biliary tree (intrahepatic cholangiocarcinoma) or from the junction, or adjacent to the junction, of the right and left hepatic ducts (hilar cholangiocarcinoma). "These endeavors elucidated an augmented GLIPR2 expression in BLCA, BRCA, cholangiocarcinoma (CHOL), amongst others, in contrast to a diminution in breast, colon, ovarian cancers, among others." (PMID 38476239, 2024).
diabetes (2 papers, 2015 to 2016). "Glipr2 is a signaling molecule, which has not been well-characterized, but is upregulated in sciatic nerve injury from experimental diabetes." (PMID 27891095, 2016).
diabetic nephropathy (2 papers, 2013). "In this study, we found that GLIPR-2 expression is elevated in the kidney tissue samples of patients with diabetic nephropathy (DN)." (PMID 23516513, 2013).
head and neck cancer (2 papers, 2019 to 2023). A primary or metastatic malignant neoplasm affecting the head and neck. "In addition, miR551b-3p targets GLIPR2 (GLI Pathogenesis Related 2) to promote tumor growth in high-risk head and neck cancer (HRHNC) by modulating autophagy." (PMID 31137914, 2019).
hepatocellular carcinoma (2 papers, 2013 to 2024). A malignant tumor that arises from hepatocytes. "Our studies demonstrate that GLIPR-2 is expressed in cancer tissues of hepatic carcinoma and can be induced in HCC cell lines in hypoxia condition in vitro." (PMID 24204846, 2013). "Furthermore, in hepatocellular carcinoma (HCC), GLIPR2’s upregulation in hypoxia contributes to migration and invasion through the hypoxia/GLIPR-2/EMT axis." (PMID 38476239, 2024). "Taken together, we provide evidence for a hypoxia/GLIPR-2/EMT/migration and invasion axis in HCC cells and it provides novel insights into the mechanism of migration and invasion of hepatocellular carcinoma cells in hypoxia condition." (PMID 24204846, 2013).
colorectal adenocarcinoma (1 paper, 2024). The most common type of colorectal carcinoma. "Noteworthy observations include CESC (AUC=0.977), CHOL (AUC=0.975), COAD (AUC=0.943), colorectal adenocarcinoma (CEAD, AUC=0.988), KICH (AUC=0.924), LUAD (AUC=0.987), LUSC (AUC=0.994), and PAAD (AUC=0.925), thereby reinforcing the diagnostic potential attributed to GLIPR2." (PMID 38476239, 2024).
colorectal cancer (1 paper, 2024). A primary or metastatic malignant neoplasm that affects the colon or rectum. "In the realm of colorectal cancer (CRC), GLIPR2’s correlation with glycolysis-related genes and its involvement in epithelial-to-mesenchymal transition (EMT) suggested its pivotal role in tumor progression." (PMID 38476239, 2024).
head and neck squamous cell carcinoma (1 paper, 2025). A squamous cell carcinoma that arises from any of the following anatomic sites: lip and oral cavity, nasal cavity, paranasal sinuses, pharynx, larynx, and salivary glands. "miR-551a functions as an oncogene in head and neck squamous cell carcinoma by targeting GLIPR2 mRNA, which modulates autophagy." (PMID 40621499, 2025).
liver cancer (1 paper, 2013). An epithelial or non-epithelial malignant neoplasm that arises from the liver. "In this study, we found that GLIPR-2 expression increased in HCC cells partially in the liver cancer paraffin-embedded tissue sections." (PMID 24204846, 2013). "To determine whether GLIPR-2 is expressed in human HCC tissues, we detected 5 paired liver cancer paraffin-embedded tissue sections by immunohistochemistry against GLIPR-2." (PMID 24204846, 2013).
cancer (7 papers, 2013 to 2025). A tumor composed of atypical neoplastic, often pleomorphic cells that invade other tissues. "Employing ROC and KM analyses, we unveiled the diagnostic and prognostic potential of GLIPR2 across diverse cancers." (PMID 38476239, 2024). "Our study observed a significant downregulation of GLIPR2 expression in most types of cancer, accompanied by a simultaneous increase in the mutation rates associated with methylation events." (PMID 38476239, 2024). "Previous studies observed that genes such as CA9, CKB and GLIPR2 were strongly associated with the prognosis of cancer." (PMID 36341424, 2022). "Strategies aimed at reversing or mitigating the methylation alterations linked to GLIPR2 downregulation could represent novel therapeutic interventions in cancer treatment." (PMID 38476239, 2024). "The observed correlation between GLIPR2 downregulation and increased methylation mutation rates suggests a potential mechanism through which cancer cells may evade the tumor-suppressive effects of GLIPR2." (PMID 38476239, 2024). "It is associated with poor survival miR-551a directly targets GLIPR2 mRNA, which is a negative regulator of autophagy, and its overexpression leads to reduced GLIPR2 levels, thereby modulating autophagy and affecting the cancer cells’ response to treatment." (PMID 40621499, 2025). "This dual phenomenon suggests a potential role of GLIPR2 in cancer pathogenesis and highlights the intricate relationship between gene expression regulation and epigenetic modifications." (PMID 38476239, 2024). "In conclusion, this study utilized diverse bioinformatics approaches to comprehensively investigate the roles of GLIPR2 in NSCLC, highlighting its potential implications in cancer development, diagnosis, mutation, methylation, and immune infiltration." (PMID 38476239, 2024). "Differential expression analysis, diagnostic curve evaluation, mutation scrutiny, methylation analysis, and examination of immune infiltration collectively depict the pivotal role of GLIPR2 in cancer pathogenesis." (PMID 38476239, 2024). "In concise summation, the prominent role of GLIPR2 in shaping the landscape of immune infiltration across diverse cancers is manifest, firmly positioning it as a compelling candidate for pioneering immunotherapeutic interventions within the realm of oncology." (PMID 38476239, 2024). "In this present investigation, we employed a comprehensive array of bioinformatics analytical methodologies to investigate the potential implications of the GLIPR2 gene in cancer progression." (PMID 38476239, 2024). "Collectively, these studies, including our own, underscore GLIPR2’s versatile roles in autophagy, cancer, and immune response, emphasizing its significance as a diagnostic marker and therapeutic target across diverse pathological conditions." (PMID 38476239, 2024). "Subsequently, KM analysis was employed to assess the prognostic value of pan-cancer GLIPR2 levels in patients." (PMID 38476239, 2024). "The integration of bulk and single-cell RNA sequencing facilitated elucidation of relationships among cellular heterogeneity, immune infiltration, and GLIPR2 levels in pan-cancer." (PMID 38476239, 2024). "Immunohistochemistry provided insights into GLIPR2 expression patterns in a multicenter cohort spanning various cancer types." (PMID 38476239, 2024). "Employing the metrics of TMB and HRD, the potential of GLIPR2 as an indicator of immunotherapeutic responses across diverse cancer types was ascertained." (PMID 38476239, 2024). "Our findings elucidated a discernible positive correlation of GLIPR2 with most immunomodulatory elements across various cancers, including kidney papillary cell carcinoma (KIRC), OV, pan-kidney cohort (KIPAN), LIHC, BRCA, LUAD, THCA, PAAD and BLCA." (PMID 38476239, 2024). "Cumulatively, these findings intimated that GLIPR2 evinced dysregulation across diverse cancer types, thus postulating its pivotal involvement in the sphere of cancer diagnosis." (PMID 38476239, 2024).
cancer (continued). "In the context of our comprehensive pan-cancer analysis aimed at deciphering the immunological implications of GLIPR2, the identification of specific malignancies conducive to anti-GLIPR2 immunotherapy holds paramount significance." (PMID 38476239, 2024). "NSCLC, known for its status as the most prevalent and lethal cancer globally, became the primary focus of our investigation following a comprehensive pan-cancer assessment of GLIPR2." (PMID 38476239, 2024). "The derived AUC values provided compelling evidence that GLIPR2 exhibited a robust capacity to effectively discriminate between malignancy and normalcy across diverse cancer types." (PMID 38476239, 2024). "Additionally, our investigation extends GLIPR2’s relevance to cancer immunity, emphasizing its role in the TME." (PMID 38476239, 2024). "Conversely, in cancers such as BLCA, KIRC, KIRP, LUSC and STAD, an elevated expression of GLIPR2 was associated with an increased risk of mortality Integrated prognostic and diagnostic analysis identified LUAD, LUSC, and CESC as cancers most likely to benefit from the GLIPR2 biomarker." (PMID 38476239, 2024). "Intriguingly, this expression pattern of GLIPR2 was robust to pan-cancer." (PMID 38476239, 2024). "Studies on GLIPR-2 gene regulating EMT in carcinogenesis may therefore yield important insights into the mechanisms of cancer metastasis as well as therapeutic treatment." (PMID 24204846, 2013). "GLIPR2, also recognized as Golgi-associated plant pathogenesis-related protein 1 (GAPR1), stands as a multifunctional protein that has garnered escalating attention due to its dual engagement in both normal cellular processes and the intricacies of cancer biology." (PMID 38476239, 2024). "Notably, the emergence of immune checkpoint (ICP) blockade proteins as promising candidates for cancer immunotherapy prompted us to conduct a meticulous evaluation of the intricate interplay between GLIPR2 expression levels and the expressions of ICP genes across various malignancies." (PMID 38476239, 2024). "Our results aligned with previous studies, revealing positive correlations between GLIPR2 expression and immune cell content in the TME across various cancers." (PMID 38476239, 2024). "In pan-cancer, particularly in LUAD, GLIPR2 emerges as a promising novel biomarker and tumor suppressor." (PMID 38476239, 2024). "Leveraging extensive datasets, including The Cancer Genome Atlas (TCGA), Genotype Tissue Expression (GTEx), Human Protein Atlas (HPA), and Clinical Proteomic Tumor Analysis Consortium (CPTAC), we conducted a comprehensive investigation into GLIPR2 expression across diverse human malignancies." (PMID 38476239, 2024).
tumor (5 papers, 2013 to 2024). "The progressive reduction in GLIPR2 expression with LUAD tumor progression suggests its potential involvement in underlying mechanisms driving LUAD development." (PMID 38476239, 2024). "In vitro functional experiments, including transwell assays, wound healing analyses, and drug sensitivity testing, were employed to delineate the tumor suppressive role of GLIPR2." (PMID 38476239, 2024). "To investigate the causal relationship between aberrant expression patterns of GLIPR2 and methylation, we utilized the UALCAN database along with OncoDB to explore abnormal GLIPR2 methylation patterns in both normal and tumor tissues." (PMID 38476239, 2024). "Copy number variations (CNV) and alterations in methylation patterns exhibited discernible correlations with GLIPR2 expression within tumor tissues." (PMID 38476239, 2024). "Furthermore, we utilized MEXPRESS to examine the correlation between GLIPR2 expression and CpG islands in tumor tissues." (PMID 38476239, 2024). "Furthermore, our in vitro experiments, while acknowledging their limitations in capturing the tumor immune microenvironment complexity, demonstrate GLIPR2 augmentation sensitizing tumor cells to radiotherapy." (PMID 38476239, 2024). "Finally, several lines of experiments indicated the tumor-suppressor function of GLIPR2 in suppressing malignant phenotype and facilitating the sensitivity of treatments." (PMID 38476239, 2024). "Notably, within GLIPR2, a total of 34 variants of uncertain significance (VUS) were identified across various tumor contexts." (PMID 38476239, 2024). "In consideration of these compelling findings, we undertook meticulous survival analyses predicated upon the levels of GLIPR2+ infiltration within the cohorts of LUAD and LUSC patients derived from Nantong Tumor Hospital." (PMID 38476239, 2024). "Our study explores the multifaceted role of GLIPR2 in NSCLC, leveraging insights from a real-world cohort at Nantong Tumor Hospital." (PMID 38476239, 2024). "Therefore, we hypothesized that GLIPR-2 is elevated in the EMT process in carcinogenesis (type 3 EMT) and involved in tumor invasion and metastasis." (PMID 24204846, 2013).
GLIPR2 also shares sentences with these, for which no sentence is quoted: glioblastoma multiforme (2 papers); infection (2); amyotrophic lateral sclerosis (1); breast invasive carcinoma (1); colon adenocarcinoma (1); dyslipidemia (1); heart diseases (1); Huntington disease (1); lung adenocarcinoma (1); non-small cell lung carcinoma (1); ovarian carcinoma (1); pancreatic adenocarcinoma (1); Parkinson's (1); prostate adenocarcinoma (1); rectum adenocarcinoma (1).